ALPL (alkaline phosphatase, biomineralization associated)
Diseases named in the same sentence as ALPL in open-access papers (continued):
Sharing a sentence is not in itself a finding about the gene and the disease.
hypophosphatasia (continued). "Hypophosphatasia (HPP), Rathbun’s syndrome, is a genetic disorder caused by genetic mutations of the ALPL gene that encodes tissue-nonspecific-isoenzyme of alkaline phosphatase (TNSALP)." (PMID 36292765, 2022). "Hypophosphatasia (HPP) is caused by loss‐of‐function mutations in the ALPL gene that encodes tissue‐nonspecific alkaline phosphatase (TNAP), whose deficiency results in the accumulation of extracellular inorganic pyrophosphate (PPi), a potent mineralization inhibitor." (PMID 34076297, 2021). "Hypophosphatasia (HPP) is a chronic, progressive bone mineralization disorder caused by loss-of-function variants in the ALPL gene encoding the tissue-nonspecific isoenzyme of alkaline phosphatase (TNSALP)." (PMID 33579333, 2021). "Hypophosphatasia (HPP) is a rare genetic disease with diverse symptoms and a heterogeneous severity of onset with underlying mutations in the ALPL gene encoding the ectoenzyme Tissue-nonspecific alkaline phosphatase (TNAP)." (PMID 32770041, 2020). "Hypophosphatasia (HPP) is an inherited disorder of defective skeletal mineralization caused by mutations in the ALPL gene that encodes the Tissue Non-specific Alkaline Phosphatase (TNSALP)." (PMID 31760938, 2019). "Hypophosphatasia (HPP) is a rare, systemic disease caused by mutation(s) within the ALPL gene encoding tissue-nonspecific alkaline phosphatase (ALP)." (PMID 30764793, 2019). "Hypophosphatasia (HPP) results from ALPL mutations leading to deficient activity of the tissue-non-specific alkaline phosphatase isozyme (TNAP) and thereby extracellular accumulation of inorganic pyrophosphate (PPi), a natural substrate of TNAP and potent inhibitor of mineralization." (PMID 26590809, 2016). "Hypophosphatasia (HPP) is caused by homozygous, compound heterozygous, or heterozygous loss-of-function mutations in the ALPL gene encoding tissue-nonspecific alkaline phosphatase (TNALP)." (PMID 26578979, 2015). "Hypophosphatasia (HPP) is a rare bone disorder caused by loss-of-function mutations in the ALPL gene, leading to deficient tissue-nonspecific alkaline phosphatase (TNAP) activity and impaired skeletal/dental mineralization." (PMID 42136733, 2026). "Hypophosphatasia (HPP), caused by loss‐of‐function mutations in the ALPL gene encoding tissue‐nonspecific alkaline phosphatase (TNAP), is characterized by skeletal and dental hypomineralization that can vary in severity from life‐threatening to milder manifestations only in adulthood." (PMID 36699639, 2023). "Hypophosphatasia (HPP) is a rare, inherited disease typically caused by genetic variants in tissue-nonspecific alkaline phosphatase (ALP, gene name ALPL) that lead to deficient enzyme activity." (PMID 40746945, 2025). "The dento-osseous bone disorder hypophosphatasia (HPP) results from disease causing variants in the gene ALPL, which encodes tissue non-specific alkaline phosphatase (TNSALP)." (PMID 40100438, 2025). "Yet another example we previously highlighted is associated with the rare metabolic disorder, hypophosphatasia (HPP), characterized by low tissue-non-specific alkaline phosphatase (TNAP) activity due to loss of function of ALPL, the gene that encodes TNAP." (PMID 39935968, 2024). "Hypophosphatasia (HPP; OMIM# 146300, 241500, 241510) is a rare hereditary disorder caused by loss-of-function mutations in the ALPL gene (MIM*171760) that encodes the tissue-nonspecific isozyme of alkaline phosphatase (TNSALP; UniprotKB# P05186)." (PMID 36613725, 2022). "Hypophosphatasia (HPP, OMIM: 146300, 241500, 241510) is a rare inherited mineral metabolism disorder caused by low enzymatic activity in the tissue nonspecific alkaline phosphatase (TNSALP) as a result of mutations (pathogenic variants) in the ALPL gene that is localized on chromosome 1p36.12." (PMID 36361766, 2022).
hypophosphatasia (continued). "Hypophosphatasia:It is a rare, inherited form of rickets or osteomalacia due to mutation (s) of the ALPL gene, resulting in reduced activity of tissue nonspecific alkaline phosphatase (TNSALP), which is marked by a low-serum alkaline phosphatase (hypophosphatasemia)." (PMID 33987622, 2021). "Hypophosphatasia (OMIM 146300, 241500, 241510) is a rare inborn error of metabolism characterized by low serum alkaline phosphatase (ALP) activity (hypophosphatasaemia) due to lossoffunction mutations within the gene that encodes the tissue-nonspecific isoenzyme of ALP (ALPL)." (PMID 30864637, 2019). "Hypophosphatasia (HPP, OMIM#241500) is a genetic condition associated with mutations in Alkaline Phosphatase Liver/bone/kidney (ALPL) gene which encodes the tissue-non-specific alkaline phosphatase isozyme (TNSALP)." (PMID 28035992, 2016). "Hypophosphatasia (HPP) is a rare genetic disorder due to deactivating variants in the ALPL gene (Chr 1p36.12, OMIM 171760) leading to deficient activity of tissue-nonspecific alkaline phosphatase (TNAP)." (PMID 40047955, 2025). "Hypophosphatasia (HPP) is a rare heterogenous inherited metabolic bone disorder caused by a loss of function mutation in the ALPL gene, resulting in the lack of tissue non-specific alkaline phosphatase (TNSALP) activity." (PMID 33889553, 2021). "Genetic sequencing of the ALPL gene in patients with AFF and controls with low alkaline phosphatase showed no abnormalities which would have resulted in hypophosphatasia." (PMID 27507156, 2016). "Hypophosphatasia (HPP; OMIM 241500, 241510, 146300) is a rare genetic disorder characterized mainly by defective bone mineralization with or without root-intact tooth loss due to inactivating variants in the ALPL gene, encoding the tissue-nonspecific alkaline phosphatase enzyme." (PMID 41158885, 2025). "Hypophosphatasia (HPP) is multi-systemic metabolic dysplasia inherited in autosomal dominant or recessive fashion, caused by loss of function mutations in the ALPL gene which encodes the tissue non-specific alkaline phosphatase enzyme (TNSALP) leading to defective bone mineralisation." (PMID 31888683, 2019).
osteomalacia (24 papers, 2010 to 2025). Disorder caused by an interruption of the mineralization of organic bone matrix leading to bone softening, bone pain, and weakness. "The indispensable function of ALPL is evidenced by the fact that newborns with mutations in the ALPL gene exhibit severe osteomalacia, foetal/perinatal lethality." (PMID 37630705, 2023). "But can bisphosphonate therapy induce osteomalacia in an asymptomatic carrier of a single ALPL mutation?" (PMID 31687651, 2019). "Individuals possessing hypomorphic ALPL (the gene encoding TNAP in humans) mutations typically present with severe rickets and osteomalacia resulting in a blockade of hydroxyapatite propagation within the ECM." (PMID 27444010, 2016).
osteosarcoma (23 papers, 2015 to 2025). A usually aggressive malignant bone-forming mesenchymal neoplasm, predominantly affecting adolescents and young adults. "On the other hand, IDH1 R132C inhibited expression of the ALPL gene in association with an increase in the repressive mark (H3K9me3), and subsequently inhibited the osteogenic properties of hMSCs and human osteosarcoma cells." (PMID 26161668, 2015). "All tested cell lines demonstrated positive ALPL staining, which is in accordance with previous observations in osteosarcoma cell lines." (PMID 37048099, 2023). "Bone is the only connective tissue producing ALPL in dogs and it can therefore be used to differentiate the canine osteosarcoma from other vimentin-positive tumors." (PMID 37048099, 2023). "Deposition of a niobium/zirconium/tantalum alloy on the surface of Ti-6Al-4V had shown unchanged expression of the alkaline phosphatase gene (ALPL) in human osteosarcoma cells (MG-63)." (PMID 36009444, 2022). "Another study showed the decreased mineralization accompanied by reduced ALPL and osterix expression in osteosarcoma cells after treatment with the RTKI imatinib and nilotinib." (PMID 35171372, 2022). "HOX transcript antisense RNA (HOTAIR) inhibited mineralization in osteoblastic osteosarcoma cells by epigenetically repressing ALPL." (PMID 31718549, 2019). "Thus, presence of vimentin combined with ALPL confirmed osteosarcoma origin of the isolated COS cells." (PMID 37048099, 2023). "One mechanism previously proposed for the supportive effects of polyP-NP supplementation on osteogenic gene expression (Col1 and ALPL) in SaOS-2 osteosarcoma cells is via the provision of metabolic energy following clathrin-mediated endocytosis of the polyP-NP." (PMID 31752206, 2019). "More interestingly, ALPL, UNC5B, and CADM1 were also highly and specifically expressed in osteosarcoma compared with most normal human organs based on the TCGA and GTEx databases." (PMID 37457661, 2023). "From MSCs to osteosarcoma, CDKN2A, ALPL, SPARC (osteonectin) and MYC were considered as origin-related factors." (PMID 34828292, 2021). "A similar gene induction after osteogenic differentiation was observed in MNNG/HOS osteosarcoma cells after exposure to CAAP (in particular, the ALPL, IGFR1, and COL3A genes induction)." (PMID 34202684, 2021). "It is well known that abnormal expression of RUNX2, ALPL, and BGLAP determines impaired molecular and cellular functions in Mg-63 and Saos-2, but this phenomenon is different in the two osteosarcoma cell lines." (PMID 31236409, 2019). "Furthermore, using CRISPR/Cas9-mediated MPP7 knockout (KO) in the human osteosarcoma HOS cell line, we demonstrate that MPP7 is critical for mineralization via regulation of ALPL expression." (PMID 41105261, 2025). "The gene expression for ALPL and COL1A1 was analyzed in the two osteosarcoma cell lines." (PMID 36835079, 2023). "Control osteosarcoma MG-63 tumour masses were introduced to the 3D bone stroma and ALPL levels were not downregulated as much as AM-1 tumour mass introduced and AM-3 tumour mass introduced 3D bone stroma models (p = 0.004 and p = 0.005 respectively)." (PMID 34916549, 2021). "Furthermore, we generated a CRISPR/Cas9-mediated MPP7 knockout in the human osteosarcoma HOS cell line and demonstrated that MPP7 deletion impairs osteogenic differentiation and completely abrogates mineralization through downregulation of ALPL expression." (PMID 41105261, 2025). "The expression of early osteogenic differentiation marker genes (i.e., ALPL, RUNX-2, and COL1A1) and the ALP enzymatic activity, whose functionally mirrors the differentiation grades of osteoblastic cells, have been reported to be involved in metastasis in osteosarcoma patients." (PMID 37175397, 2023). "AA mainly increased ALPL levels, unlike DHA, especially in osteosarcoma and chondrosarcoma CSCs." (PMID 41300532, 2025).
osteoporosis (22 papers, 2010 to 2025). A condition of reduced bone mass, with decreased cortical thickness and a decrease in the number and size of the trabeculae of cancellous bone (but normal chemical composition), resulting in increased fracture incidence. "For example, the results of the current study show that the c.1426G>A ALPL variant was associated with fractures and osteoporosis in family 1; however, this variant was previously reported in an asymptomatic individual with subclinical HPP." (PMID 40746945, 2025). "Previous genetic analyses of adults with persistently low ALP levels demonstrated ALPL variants in approximately 80% of cases, emphasizing the importance of careful diagnostic consideration before establishing a diagnosis of osteoporosis." (PMID 39685537, 2024). "Lastly, a recent study investigated the prevalence of pathogenic ALPL variants in a series of 16 hypophosphatasemic patients identified from an UK osteoporosis clinic database, finding a prevalence of 87.5%." (PMID 34213743, 2022). "The present study identified pathogenic variants of ALPL gene in one-fourth of hypophosphatasemic outpatients referred for diagnosis and management of osteopenia/osteoporosis, CTIBL and/or fragility fractures." (PMID 34213743, 2022). "In contrast, a single study of 3285 patients referred to an osteoporosis clinic, reported a higher prevalence of patients with an ALPL variant (14 out of 16 patients with hypophosphatasaemia) including four subjects treated with BPs." (PMID 34258332, 2021). "We searched for patients with low ALP in a cohort of 3285 patients referred to an osteoporosis clinic over a 10‐year period and performed mutation screening of ALPL in those with low ALP (≤40 U/L) on two or more occasions." (PMID 31793067, 2020). "We conclude that heterozygous loss‐of‐function mutations in ALPL are common in osteoporosis patients with low ALP." (PMID 31793067, 2020). "There is clearly still much to learn about adult HPP, in particular how to manage the frequently encountered patients with osteoporosis alongside mild or asymptomatic HPP with a single ALPL mutation." (PMID 31687651, 2019). "Should heterozygous ALPL mutation carriers with osteoporosis be treated differently, then, to other individuals with osteoporosis?" (PMID 31687651, 2019). "In this article, we present two cases illustrating the dilemma of managing osteoporosis in adults with heterozygous ALPL mutations, and offer some pathological insights based on bone biopsy findings." (PMID 31687651, 2019). "Considering clinical features and vitamin B6-related biomarkers may be more useful in predicting the detection of the aberrant ALPL variants in adult patients with osteopenia/osteoporosis and/or fragility fractures." (PMID 34213743, 2022). "In the ALPL- group most fractures were associated to osteoporosis." (PMID 34258332, 2021). "Antiresorptive treatment is a frequent reason for hypophosphatasaemia and effects of these agents in adults with a variant in ALPL and osteoporosis remain unclear and require further studies." (PMID 34258332, 2021). "Therefore, the aim of this study was to investigate how frequently low ALP occurs in patients with osteoporosis and to determine the proportion of these individuals who have mutations in ALPL." (PMID 31793067, 2020). "Osteoporosis is a significant cause of morbidity in β‐thalassemia, and downregulation of ALPL expression by more than 30‐fold in D provides an important clue as to how that may develop." (PMID 31134759, 2019). "It is of interest, however, that missense variants in ALPL were significantly overrepresented in the osteoporosis clinic population with low ALP values compared with the general population, indicating that these variants may be a predisposing factor for osteoporosis." (PMID 31793067, 2020).
osteoporosis (continued). "Osteoporosis is one of the leading causes of morbidity in individuals with β‐thalassemia, and the ALPL (alkaline phosphatase) gene required for proper osteoblast function was 33‐fold downregulated in D compared to N. This reduction in expression may be a regulatory consequence of iron overload." (PMID 31134759, 2019). "Single nucleotide polymorphisms in genes critical for bone homeostasis, including ALPL, DKK1, PHEX, and COL1A1, are associated with osteoporosis and related skeletal pathologies in humans." (PMID 40961770, 2025). "We have found that about 0.5% of patients attending our osteoporosis clinic had low circulating concentrations of ALP and that the majority of these individuals had pathogenic mutations in ALPL." (PMID 31793067, 2020). "However, the initial sequencing of 70 genes for early onset osteoporosis including the ALPL gene did not reveal any ALPL variants." (PMID 33191482, 2021). "However, the high carrier frequency of ALPL variants also implies that asymptomatic carriers and individuals with subclinical HPP may be incidentally found when screening for osteoporosis, with a risk of misdiagnosis of HPP particularly among postmenopausal women." (PMID 41286962, 2025). "Our data also revealed an upregulated expression of ALPL and BGLAP in patients with osteoporosis." (PMID 37339951, 2023). "Peripheral blood DNA from 22 patients (mean age ± SEM, 56.7 ± 2.4 years, 17 females, 5 males) referred for the evaluation of osteopenia/osteoporosis, fragility fractures or CITBL presenting persistent unexplained hypophosphatasemia was screened for genetic aberrations of the ALPL gene." (PMID 34213743, 2022). "Expression levels of ALPL, BGLAP, and TNF were not significantly different between control and osteoporosis groups, but those of ACP5 and CTSK were significantly increased in patients with osteoporosis compared to those in the controls." (PMID 37339951, 2023).
rickets (21 papers, 2010 to 2025). Bone softening and weakening usually caused by deficiency or impaired metabolism of vitamin D. Deficiency of calcium, magnesium, or phosphorus may also cause rickets. "About the eight novel amino acid changes, the ALPL database has two different records for residue Glu84 (#18): the first was 84Val found in a family with autosomal dominant odonto-hypophosphatasia also characterized by rickets-like signs." (PMID 37600704, 2023).
Obesity (9 papers, 2017 to 2025). Accumulation of substantial excess body fat. "In our study, a structural deletion near the ALPL (Alkaline Phosphatase, Biomineralization Associated) gene was associated with reduced body weight and a higher risk of obesity." (PMID 37799139, 2023). "This study identified one novel marker ALPL of neutrophil activation in response to obesity and provided evidence that obesity induced change in ALPL expression was associated with CVD risk factors." (PMID 30837522, 2019). "Incorporating with our observation that obesity is associated with higher transcription and translation of ALPL in neutrophils, directly study of serum NAP might provide an explanation for the serum ALP associated CVD risks." (PMID 30837522, 2019). "Elevated ALPL levels are correlated with cardiovascular risk factors, including systolic/diastolic blood pressure, mean arterial pressure, carotid intima–media thickness, and a trend toward higher fasting insulin, a consistent and novel neutrophil activation marker in obesity." (PMID 40943443, 2025). "The polymorphisms of mineralization genes, such as ALPL, are reported to be directly related to obesity according to recent publications, hence indicating the accompanying role of ALPL for obesity." (PMID 29258237, 2017). "The group × gender interaction was not significant (p = 0.177), indicating that obesity associated higher expression of ALPL exits in both males and females." (PMID 30837522, 2019). "In mice, the targeted removal of ALPL specifically in adipocytes leads to decreased overall energy expenditure and the onset of obesity, without affecting movement or feeding behavior." (PMID 37799139, 2023).